VDR (vitamin D receptor)
Diseases named in the same sentence as VDR in open-access papers (continued):
Sharing a sentence is not in itself a finding about the gene and the disease.
liver fibrosis (continued). "Because VDR possesses potent antifibrotic activities in the liver, it is tempting to speculate that IGFBP5 might regulate liver fibrosis by functioning as an inhibitor of VDR." (PMID 38092723, 2023). "Moreover, the expression of VDR in the mild liver fibrosis group was significantly stronger than that in the severe liver fibrosis group." (PMID 35043727, 2022). "As a selective VDR agonist, calcipotriol also presents potential value in anti-liver fibrosis." (PMID 35043727, 2022). "Finally, we used the CCl4-induced rat liver fibrosis model to explore the anti-liver fibrosis effects of VDR and calcipotriol." (PMID 35043727, 2022). "Moreover, the correlation analysis showed that the expression of VDR was negatively correlated with the degree of liver fibrosis and the expression of α-SMA and Col-1." (PMID 35043727, 2022). "MiR-125a can target VDR to promote the occurrence and progression of liver fibrosis." (PMID 36304947, 2022). "More studies are needed to clarify the role of VDR in attenuation of liver fibrosis." (PMID 32276660, 2020). "In order to determine whether changes in CD107a and VDR on NK1.1 cells could modulate liver fibrosis; we co-cultured NK1.1 cells from mice livers from all groups with WT pHSCs through an in vitro setting assay to assess cytotoxicity/killing potential." (PMID 32276660, 2020). "In this study, we employ calcipotriol, a potent VDR agonist, to test its therapeutic effect in cholestasis, determine whether VDR can modulate NLRP3 to inhibit HSC activation and alleviate liver fibrosis and injury, and explore the underlying mechanism." (PMID 32296329, 2020). "Although the liver has a very low or undetectable level of VDR expression, hepatic stellate cells are a clear target, as selective VDR deletion causes hepatic fibrosis and a state of nonalcoholic liver disease." (PMID 30321335, 2019). "This study aims to investigate whether the common VDR polymorphisms are associated with the response to PEG-IFN-based therapy and advanced liver fibrosis in patients with chronic HCV infection." (PMID 31565578, 2019). "A recent study found that miR-351 mediated schistosome-induced hepatic fibrosis by targeting VDR." (PMID 31888743, 2019). "Additionally, VDR is expressed in hepatic stellate cells, which are major producers of cellular matrix and the main indicators of liver fibrosis." (PMID 28685131, 2017). "Stimulation of VDR in activated HSCs inhibits their proliferation and suppresses collagen production, explaining the anti-fibrotic effects of vitamin D supplementation in the rat model for liver fibrosis." (PMID 23540496, 2013). "VDR expressions affect trNKT cells activity and could modulate progressions of liver fibrosis." (PMID 39654627, 2024). "Therefore, p62 may act as a negative regulator of liver fibrosis by stimulating VDR signaling in HSCs." (PMID 37175993, 2023). "Interestingly, vitamin D receptor knock out (VDRKO) mice developed spontaneous liver fibrosis." (PMID 33868174, 2021). "Moreover, the progression of liver fibrosis has been associated with the existence of VDR polymorphisms in patients with PBC10 and HCV18 and with reduced full-length VDR protein expression, but increased VDR protein fragments in patients with NAFLD10,18,19." (PMID 30218108, 2018). "CAL has been extensively studied as a synthetic VDR agonist that can neutralize TGF‐β1 and reduce liver fibrosis." (PMID 37638336, 2023). "In the presence of the ligands, the vitamin D receptor (VDR) occupies Smad3-binding sites at profibrotic genes and reduces TGF-β-mediated hepatic fibrosis." (PMID 35359452, 2022). "Abramovitch and colleagues showed, in 2011, that ligation of VDR in HSCs inhibited their proliferation, and activation and reduced thioacetamide (TAA)-induced liver fibrosis in rats." (PMID 29659559, 2018). "VDR is highly expressed in hepatic stellate cells (HSC), indicative of its role in regulating liver fibrosis." (PMID 27456065, 2016).
liver fibrosis (continued). "ANGPTLs were novel transcription targets of VDR and activated VDR upregulated hepatic and systemic ANGPTLs expression in NAFLD patients, thus increasing lipid synthesis and intrahepatic fat accumulation and aggravating liver fibrosis." (PMID 37180779, 2023). "Similarly, VDR ablation abolishes the antagonistic effect of 1,25(OH)2D3 on TGF-β-promoted hepatic fibrosis." (PMID 35359452, 2022). "VDR is not expressed in liver tissue, so the role of vitamin D in liver fibrosis has not been studied in depth for a long time." (PMID 34615940, 2021). "Definitive clinical data for liver fibrosis patients with vitamin D or VDR agonist treatment are lacking." (PMID 29659559, 2018). "Moreover, a possible role for vitamin D in liver fibrosis has gained further support from the finding that VDR is expressed in human as well as in rat liver non-parenchymal cells, such as Hepatic stellate cells (HSCs)." (PMID 32276660, 2020). "Notably, we found that VDR activation can induce YAP1 expression at the transcriptional level in liver tissue and HSC line and increased YAP1 further exerts its inhibitory effect on NLRP3 expression to alleviate cholestatic liver fibrosis and injury." (PMID 32296329, 2020). "The cell-specific expression pattern of VDR suggests that the liver could be responsive to vitamin D during liver fibrosis through its non-parenchymal cells, in particular, HSCs." (PMID 29659559, 2018). "Strikingly, vitamin D receptor was demonstrated to be key in the control of liver fibrosis by affecting SMAD3-mediated transcriptional response in mouse model, supporting the notion that this pathway might be essential in the control of liver fibrosis." (PMID 24391588, 2013). "However, another report showed that activation of VDR did not improve the manifestation of preexisting pathology despite inhibiting the development of hepatic fibrosis by inhibiting collagen type I alpha 1 chain (COL1A1), tissue inhibitor of metalloproteinase (TIMP1) and α-SMA." (PMID 39478961, 2024). "In HSCs, VDR activation has been reported to potently repress TGFβ-induced profibrotic gene expression by antagonizing SMAD-dependent transcriptional programs, suggesting that targeting VDR with less calcemic ligands might be beneficial for the prevention and treatment of liver fibrosis." (PMID 35203271, 2022). "However, VDR mechanism in liver fibrosis modulations is not well understood." (PMID 32276660, 2020).
Hypercalcemia (51 papers, 2007 to 2026). An abnormally increased calcium concentration in the blood. "Hypercalcemia is a highly specific adverse reaction of all VDR agonists, but the relative risk of hydroxylated precursors was found to be higher than that of cholecalciferol." (PMID 39770528, 2024). "Numerous VD analogues have been designed as potent VDR agonists with higher VDR binding affinity, but with lower hypercalcemia risk." (PMID 35734414, 2022). "The association of 1,25D3 treatment with hypercalcemia is in part related to VDR-mediated expression of the epithelial Ca2+ channel TRPV6 (transient receptor potential vanilloid type 6)." (PMID 29030554, 2017). "1,25(OH)2D3, acting through the VDR, causes hypercalcemia leading to failure of multiple organs at doses as low as 0.1 μg/kg." (PMID 28039464, 2017). "Intestinal activation of the VDR can cause hypercalcemia and hyperphosphatemia by enhanced intestinal absorption." (PMID 23509710, 2013). "Paricalcitol has more selective activation of VDR in the parathyroid gland over that in the intestine and bone and offers the possibility of minimizing the risk of hypercalcemia and hyperphosphatemia, while still significantly reducing PTH." (PMID 23509710, 2013). "Inhibitors against VDR are expected to be effective therapeutic agents for bone Paget’s disease, which occurs when the sensitivity of VDR to F0 is abnormally increased, and for hypercalcemia, which is caused by vitamin D overload and other factors." (PMID 41533263, 2026). "The logistic regression analysis demonstrated that the association of VDR agonists, overdosing, concomitant administration of calcium salts, drug interactions with thiazide diuretics and lithium, and dehydration significantly increase hypercalcemia risk." (PMID 39770528, 2024). "Hypercalcemia was a hallmark ADR for all VDR agonists, with the highest risk linked to dihydrotachysterol (ROR = 5668; 95%CI = 3332 to 9641; p < 0.0001), alfacalcidol (ROR = 965.7; 95%CI = 843.6 to 1106; p < 0.0001), and calcitriol (ROR = 726.0; 95%CI = 634.6 to 830.5; p < 0.0001)." (PMID 39770528, 2024). "In order to understand the link between VDR agonists and hypercalcemia, the current study implemented a multiple logistic regression analysis, which showed that dehydration and overdose were the most important risk factors for developing hypercalcemia." (PMID 39770528, 2024). "The association between hypercalcemia and VDR agonists was analyzed by calculating the proportional reporting ratio (PRR) and the reporting odds ratio (ROR) along with 95% confidence interval (95%CI) for each compound that had the minimum of three cases registered." (PMID 39770528, 2024). "However, the disproportionality analysis showed that only active VDR agonists (e.g., calcitriol, alfacalcidol) were associated with severe complications like renal and urinary disorders and cardiac issues due to hypercalcemia." (PMID 39770528, 2024). "The co-administration of multiple VDR agonists was also found to increase hypercalcemia risk." (PMID 39770528, 2024). "Furthermore, the disproportionality analysis showed that the possible consequences of hypercalcemia such as nephrolithiasis, cardiac disorders, neurological disorders, and pancreatitis were associated with active (i.e., 1α-hydroxylated derivatives) VDR agonists only." (PMID 39770528, 2024). "Furthermore, the combination of VDR agonists posed the greatest risk of hypercalcemia." (PMID 39770528, 2024). "Despite the fact that hypercalcemia might cause gastrointestinal symptoms, cholecalciferol and ergocalciferol were more frequently associated with abdominal pain and discomfort than other VDR agonists." (PMID 39770528, 2024). "HPHPT chief cell patterns show a marked CaSR decreased expression along with an increased CYP27B1/VDR expression, suggesting an appropriate autocrine/paracrine counterregulation to hypercalcemia/high PTH." (PMID 41907687, 2026).
Hypercalcemia (continued). "The first shift moved beyond simple calcitriol replacement with the development of selective vitamin D receptor activators (VDRAs) designed to minimize hypercalcemia while maximizing PTH suppression." (PMID 41515987, 2025). "Although vitamin D acts as a natural VDR agonist, its therapeutic application is constrained by hypercalcemia risks." (PMID 40514735, 2025). "This direct VDR activation, however, increases the risks of hypercalcemia, accelerated catabolism, and the induction of FGF23 (a topic central to Paradigm Shift 3)." (PMID 41515987, 2025). "Key uncertainties remain, including tissue heterogeneity of VDR expression, optimal dosing windows and target 25(OH)D ranges for cervical endpoints, and safety at higher exposures such as hypercalcemia." (PMID 41245397, 2025). "Vitamin D toxicity due to VDR activation is usually diagnosed based on elevated serum 25-hydroxy vitamin D levels accompanied by hypercalcemia and hypercalciuria." (PMID 39770528, 2024). "Already in the first studies on active vitamin D hypercalcemia and hyperphosphatemia, due to increased absorption induced by vitamin D receptor activators, in the gut were reported." (PMID 38397979, 2024). "Upon binding with the Vitamin D receptor, 1,25-dihydroxyvitamin D3(1,25D) directly inhibits parathyroid hormone gene transcription and antagonizes osteocalcin to prevent hypercalcemia." (PMID 39872315, 2024). "It is considered a selective activator of the vitamin D receptor (VDR) that has a better safety profile regarding hypercalcemia than vitamin D. VDR is expressed by multiple cell types, including VSMC and immune system cells." (PMID 38732029, 2024). "Still, extracorporeal treatments rapidly reduce excessive concentrations of 25-OH-vitamin D3, which have been shown to directly activate the vitamin D receptor, thereby maintaining hypercalcemia." (PMID 36547775, 2023). "While FGF23 represses CYP27B1 and activates catabolism of active hormone, increased PTHLH secretion can lead to hypercalcemia via inactivation of VDR." (PMID 37242266, 2023). "Two challenges that limit VDR agonist use clinically are hypercalcemia and the cooperation of VDR with ERG to hyper-induce the 1α,25-dihydroxyvitamin D3 metabolizing enzyme, CYP24A1, thus reducing VDR activity." (PMID 28591703, 2017). "However, excessive calcitriol levels or heightened sensitivity of the vitamin D receptor (VDR) can lead to hypercalcemia, motivating the search for analogues that preserve therapeutic activity while reducing adverse effects." (PMID 41562276, 2026). "Moreover, novel VDR antagonists such as ZK168281 demonstrate potential to suppress hypercalcemia and vitamin D toxicity by inhibiting transcriptional activity and altering VDR localization." (PMID 41828612, 2026). "The Epfn KO, MEM1 cKO, and PTH‐CyclinD1 TG mouse models are associated with hypercalcemia, while the CaSR, Cyp27b1, and VDR KO mouse models have a normal serum calcium level despite elevated PTH due to impaired calcium absorption in the kidneys and intestine." (PMID 40164571, 2025). "In other words, the odds ratio values calculated by exp (coefficient) showed that those patients which were diagnosed with dehydration and used and overdose of VDR agonist had an odd ratio (95% CI) of 5.05 (2.45–10.4) and 3.62 (2.84–4.62), respectively, to develop hypercalcemia." (PMID 39770528, 2024). "Hypercalcemia (49; 0.64%) was reported in a smaller proportion than for other VDR agonists." (PMID 39770528, 2024). "Calcitriol binds to the VDR with a very high affinity and triggers hypercalcemia even at low doses." (PMID 39898321, 2024). "In addition, in VDR−/− mice, hypercalcemia showed a significant decrease in the 1α-hydroxylase protein levels in bone, but not in its gene expression, and only a tendency to decrease it in the kidney." (PMID 35807756, 2022).
Hypercalcemia (continued). "However, since hypervitaminosis D leads to increased calcium absorption via the upregulation of intestinal VDR, a strict calcium-reduced diet is mandatory to protect patients from hypercalcemia." (PMID 35458137, 2022). "As ZK168281 also blunts 1α,25(OH)2D3-induced VDR signaling in fibroblasts of a patient with impaired vitamin D degradation, this VDR antagonist represents a promising therapeutic option for 1α,25(OH)2D3-induced hypercalcemia." (PMID 33288743, 2020). "VDR regulates calcium metabolism and high levels of 1,25D(OH)2D3 result in hypercalcemia." (PMID 28591703, 2017). "A critical limitation of studies using VDR agonists is the possibility of hypercalcemia." (PMID 28591703, 2017). "This supports our hypothesis that novel chemical scaffolds with tissue selective VDR modulation properties will be devoid of hypercalcemia." (PMID 28814738, 2017). "Through activation of VDR, calcitriol triggers increased reabsorption of calcium and phosphate in the kidneys, increased calcium absorption from the intestine, and bone mineralization, leading eventually to the development of hypercalcemia and hyperphosphatemia." (PMID 41373702, 2025). "Third, there were no data on the usage of calcium supplements, vitamin D receptor activators, and other medications that may affect calcium metabolism; therefore, the risk of death associated with hypercalcemia may be affected." (PMID 36619536, 2022). "Probably,residual VDR agonistic effects in 2 and 3 arise because the A-ring is accessible for interactions with 1-αhydroxylase; for similar reasons, 2 and 3 may also exhibit hypercalcemia if administered in animals." (PMID 35404047, 2022). "Additionally, our case is the first one that demonstrate tumor 1α-hydroxylase activity and vitamin D receptor expression, which could explain the increased levels of calcitriol and subsequent hypercalcemia." (PMID 35154010, 2021). "As paricalcitol is a vitamin D receptor agonist that diffuses through the blood-brain barrier and shows relatively few side effects such as hypercalcemia and hyperphosphatemia, it may be a more appropriate neuroprotective drug than vitamin D itself for clinical applications." (PMID 32522270, 2020). "Hypercalcemia associated with late fibrosis may inhibited VDR levels, however, may not explain the profibrogenic effects of vitamin D." (PMID 32276660, 2020). "Moreover, they generated two synthetic ligands that selectively inhibit TGF-β-SMAD signal transduction without activating vitamin D receptor (VDR)-mediated transcription or causing hypercalcemia." (PMID 29270765, 2018). "The most common drugs currently used to treat secondary hyperparathyroidism in China were calcium-based phosphorus binders and non-selective VDR activator medications which may cause recurrent hypercalcemia and hyperphosphataemia." (PMID 26058796, 2015). "While the exact mechanism underlying vitamin A-induced hypercalcemia has not been fully elucidated, it is believed to involve increased osteoclastic activity, reduced osteoid formation, suppression of osteoblastic activity, and impaired vitamin D receptor function." (PMID 39897231, 2025). "The widespread distribution of VDR also reduces the amount of CAL arriving at the targeted site and induces possible adverse effects, such as hypercalcemia." (PMID 37638336, 2023). "Experimental hypercalcemia was induced by calcium gluconate injection in thyro-parathyroidectomized (T-PTX) VDR +/+ and VDR−/− mice with constant PTH infusion." (PMID 35807756, 2022). "In T-PTX VDR +/+ and VDR−/− mice with constant PTH levels, hypercalcemia induced an increase in FGF23 levels, but to a lower extent in animals lacking VDR." (PMID 35807756, 2022). "Taken together, our results show that the vitamin D analog ZK impairs 1,25D3-induced VDR nuclear translocation by enhancing the interaction of the receptor with WBP4 in the cytosol, and prevents and/or normalizes 1,25D3-induced hypercalcemia in mice." (PMID 33288743, 2020).